BRCA1 (BRCA1 DNA repair associated)
Diseases named in the same sentence as BRCA1 in open-access papers (continued):
Sharing a sentence is not in itself a finding about the gene and the disease.
breast cancer (continued). "Elucidation of specific and recurrent/founder pathogenic variants (PVs) in BRCA (BRCA1 and BRCA2) genes can make the genetic testing, for breast cancer (BC) and/or ovarian cancer (OC), affordable for developing nations." (PMID 35216584, 2022). "The CCK-8 results for ER-positive MCF-7 breast cancer cells and BRCA1-mutant HCC1937 breast cancer cells were similar to those for MDA-MB-231 cells." (PMID 35563196, 2022). "We observed a positive correlation between BRCA1/2 overexpression and poor patient survival in breast cancer (p < 0.01)." (PMID 35409110, 2022). "Olaparib was initially approved for BRCA1/2 mutant ovarian and breast cancer patients, which is the basis for studies in these model systems that elaborated the association between Olaparib and autophagy." (PMID 37304006, 2022). "The identification of novel targeted treatment approaches is of high importance for patients with BRCA1-mutant breast cancer to overcome failure of a chemotherapy or resistance to PARP inhibition." (PMID 35715861, 2022). "The important factors which increase a man’s risk of breast cancer are; older age, “BRCA2/BRCA1” mutations, and increased estrogen levels, genetic history in family, and highly exposure to radiation." (PMID 35145999, 2022). "Our findings reveal an approach to improve the response of BRCA1-mutant breast cancers to PARPi therapy." (PMID 35641483, 2022). "Rare germline variants in the high-risk genes BRCA1 and BRCA2 together with the moderate-risk genes such as PALB2, ATM, CHEK2, and BRIP1 account for about 30% of breast cancer predisposition." (PMID 34755241, 2022). "In our study, five mutations (in BRCA1 and in BRCA2) were OCCRs, which means they had higher ovarian cancer risk and lower breast cancer risk than mutations in other regions." (PMID 35205313, 2022). "In carriers of the BRCA1 and BRCA2 pathogenic variants, prophylactic mastectomy reduces the risk of subsequent breast cancer by approximately 90%." (PMID 36580360, 2022). "disclosed that BP1 homeoprotein repressed BRCA1 expression by direct binding to its first intron in sporadic breast cancer." (PMID 35883028, 2022). "Our study showed that it is mandatory to consider the complex interplay between the types of BRCA1 and BRCA2 pathogenic variants, age at primary breast cancer diagnosis, breast cancer subtype and stage, and received systemic treatment." (PMID 36580360, 2022). "Since the discovery of the breast cancer susceptibility genes, BRCA1 and BRCA2, various other genes conferring an increased risk for breast cancer have been identified." (PMID 35039564, 2022). "The impact of RRBSO in patients with the BRCA1 and BRCA2 pathogenic variants with luminal breast cancer in stage I/II increased with age." (PMID 36580360, 2022). "Loss of Brca1 in p16 or p18 deficient mice activates EMT and induces BLBCs, whereas, loss of p18 induces luminal type mammary tumors." (PMID 35236825, 2022). "Carriers of BRCA1 and BRCA2 variants have cumulative breast cancer risks of 72% and 69%, respectively, and cumulative ovarian cancer risks of 44% and 17%, respectively, up to the age of 80 years, which is remarkably higher than those of the general population." (PMID 35627717, 2022). "The majority of breast cancers are sporadic, but 10–20% of total patients diagnosed with TNBC have a mutation in BRCA1 or BRCA2." (PMID 35158750, 2022). "Therefore, our results might suggest a context where Tgfβr2 might contribute to malignancy in human TNBC and reveal, for the first time, that a targetable TGFβR signaling pathway is directly activated by BRCA1-deficiency in the induction of EMT in breast cancers." (PMID 35236825, 2022). "In our case, the same germline BRCA1 was detected in our patient and observed in the mother with breast cancer." (PMID 36463302, 2022).
breast cancer (continued). "Although it is universally indicated, BRCA1/2 testing was performed in only 31% of males with breast cancer, and 17.4% of women with ovarian cancer in a study of commercially insured patients in the USA13." (PMID 35190596, 2022). "Here, we show that HspBP1 plays an important role in inhibiting breast cancer tumorigenesis by promoting BRCA1-mediated HR repair." (PMID 35387978, 2022). "We also show that the loss of TSG101 in connection with inactivated tumor suppressors BRCA1/2 in breast cancer cells is lethal." (PMID 36124865, 2022). "Statistically significant pre-post changes were obtained in awareness of mutations in breast cancer predisposition genes BRCA1 and BRCA2, breast density, and lifestyle choices affecting breast cancer risk." (PMID 35209930, 2022). "Clinical trials evaluating the oral PARP inhibitor olaparib in BRCA1/2-positive metastatic breast cancer are currently underway, with interim results showing efficacy." (PMID 35744786, 2022). "The present study used a systematic multiomics approach to investigate BRCA1/2 functions as prognostic biomarkers in breast cancer." (PMID 35409110, 2022). "Currently, science has determined the anti-breast cancer role of BARD1 in the BRCA1- dependent pathway." (PMID 35650591, 2022). "For example, miR-335-5p influences many targets in the BRCA1 cascade, affecting cell apoptosis and proliferation in breast cancer." (PMID 36030248, 2022). "From a molecular point of view, TNBCs share similarities with the basal-like breast cancer defined by Perou and Sorlie, BRCA1-related disease and claudin-low breast cancer." (PMID 35158904, 2022). "As expected, VNGD silencing resulted in growth inhibition in the MCF‐7 and MDA‐MB‐231 breast cancer cell lines, both bearing WT BRCA1." (PMID 36047643, 2022). "Mutations in DNA damage response genes, such as BRCA1 and BRCA2, observed in breast cancer are also associated with production of elevated mutation numbers, particularly of strong binder peptides to MHC molecules." (PMID 35323317, 2022). "In our population cohort, BRCA1, and BRCA2 pathogenic and likely pathogenic variants have high risk of breast cancer." (PMID 35938029, 2022). "Different risk assessment models examined performed well in predicting risk of carrying germline loss-of-function variants in BRCA1 and/or BRCA2 in breast cancer cases." (PMID 35353237, 2022). "Of interest, the expression of BRCA1 in breast cancer inversely correlates with the frequency of the CSCs." (PMID 35740092, 2022). "Similar frequencies were also previously reported in unselected Japanese breast cancer patients, with BRCA2 mutations observed in 2.71%, and BRCA1 mutations observed in 1.45% of the patients." (PMID 35494038, 2022). "For breast cancers, National Comprehensive Cancer Network (NCCN) guidelines recommend that recurrent or metastatic patients with germline BRCA1/2 mutations receive PARPi therapy." (PMID 36147908, 2022). "The results showed that there was a significant difference in BRCA1/2 alteration frequency in breast cancer." (PMID 35409110, 2022). "hsa-miR-342 and hsa-miR-146 are associated with estrogen levels, and have a role in negative regulation of BRCA1 in breast cancer." (PMID 37533517, 2022). "We also reported that two ovarian and breast cancer patients with NGS-determined BRCA1/2 LGR benefited from PARP inhibitors (PARPi)." (PMID 36147908, 2022). "In this study breast cancer onset was 4–6 years earlier for BRCA1 patients compared to patients in all other groups." (PMID 35469032, 2022).
breast cancer (continued). "The BRCA1-induced metabolic reprogramming of breast cancer cells was examined using global metabolomics and transcriptomics platforms." (PMID 35432218, 2022). "In order to enable long-range amplification and nanopore sequencing, the BRCA1 breast cancer gene's body and flanking regions are isolated from peripheral blood cells using the Cas9-assisted targeting of chromosomal segments (CATCH) method." (PMID 36030244, 2022). "The identification of novel molecular targets for a tailored treatment approach is thus of high importance to increase therapeutic options for patients with BRCA1-mutant breast cancer." (PMID 35715861, 2022). "The precision obtained for Intrahepatic cholangiocarcinoma was 0.88 and for Non BRCA1/BRCA2 familial breast cancer was 0.86." (PMID 36401182, 2022). "The current approaches of metastatic breast cancer treatment are tyrosine kinase inhibitor (lapatinib); PARP inhibitors with BRCA1 or BRCA2 gene mutation; CDK4/6 inhibitor (palbociclib); PI3 kinase inhibitors; and immunotherapy (“checkpoint inhibitors”)." (PMID 35454076, 2022). "Breast cancer genes BRCA1 and BRCA2 are tumor suppressor genes that function in DNA double-strand break repair in the homologous recombination pathway." (PMID 36439508, 2022). "For example, application 1411 was underpinned by the evidence linking BRCA1/2 testing in breast cancer probands, and this was used to support public funding for BRCA1/2 testing in breast cancer probands and ovarian cancer probands." (PMID 34570356, 2022). "Several pathogenic CNVs in special genes have been reported in the beginning and development of breast cancer subtypes, including BRCA1, MTUS1, and hTERT, suggesting that CNVs also play a unique role in breast cancer." (PMID 36685905, 2022). "The risks of developing male breast cancer compared with the general population have been estimated to be 15- to 18-fold higher for BRCA1 and 80-fold higher for BRCA2 carriers." (PMID 34320204, 2022). "Mutations in BRCA1 and BRCA2, which cause Hereditary Breast and Ovarian Cancer Syndrome (HBOC), account for around 80% of the 5%–10% of breast cancer cases related to rare mutations." (PMID 35128817, 2022). "Although BRCA1/2 mutations are enriched in patients with EOC who are <50 years old at diagnosis and/or have a family history of ovarian or breast cancer, restricted testing criteria will miss a significant portion of BRCA1/2 germline mutation carriers." (PMID 35735457, 2022). "While downregulation of BRCA1 resulted in a significant increase in CSC-like populations, a significant decrease in CSC-like populations was observed in breast cancer cells after reconstitution of BRCA1." (PMID 36612206, 2022). "The majority of BRCA1-mutant breast cancers are characterized by a triple-negative phenotype and a basal-like molecular subtype, associated with aggressive clinical behavior." (PMID 35715861, 2022). "ART558 sensitivity was also confirmed ex vivo in tumor organoid derived from BRCA1-mutant breast cancer, which was also sensitive to olaparib." (PMID 36613762, 2022). "Subsequently, we carried out Spearman rank correlation analysis of UBE2T and breast cancer genes (BRCA1, BRCA2)." (PMID 36088429, 2022). "Breast cancer patients enrolled under the Malaysian Breast Cancer Genetic Study between October 2002 and February 2018 were tested for BRCA1, BRCA2 and PALB2 genes." (PMID 35167615, 2022).
breast cancer (continued). "The first published case report of mosaicism was in a 39 year old woman with bilateral breast cancer and a mosaic BRCA1 exon 16 deletion in blood and tumour." (PMID 36068545, 2022). "For breast cancer, several genes such as BRCA1, BRCA2, PALB2, ATM, and CHEK2 act as high- to moderate-penetrance cancer susceptibility genes." (PMID 35853889, 2022). "BRCA1/BRCA2 mutations and aberrant expression are common as the hallmarks of ovarian and breast cancer." (PMID 35328651, 2022). "Mutations of breast cancer gene-1 (BRCA1) and BRCA2 were also analyzed with respect to CDH family gene expressions, which represent breast cancer oncogenes." (PMID 36315446, 2022). "Up to 10% of breast cancer is due to genetic predisposition, with inherited mutations in breast cancer gene 1 (BRCA1) or BRCA2 (herein referred to as BRCA1/2) accounting for most cases." (PMID 35025760, 2022). "It has been shown that BRCA1 expression (well-known tumor suppressor gene in breast cancer) is decreased by transcription factors such as Slug, while at the same time Slug stability is reduced by BRCA1 gene expression." (PMID 35659296, 2022). "Factors associated with persistently high cancer concerns were age below 35 (BRCA1) or 40 (BRCA2), unemployment, previous breast cancer, lower education and a more recent BRCA1/2-PV diagnosis." (PMID 34997316, 2022). "With the aim of comprehensively covering the topic of the prognostic role of BRCA1/2 mutations in breast cancer, in this study, we first analyzed the expression of BRCA1/2 in breast cancer tissues and normal tissues." (PMID 35409110, 2022). "BRCA1 mutations seem to play a smaller role in MBC compared with female breast cancer, as BRCA2 mutations are more significantly associated with MBC than BRCA1." (PMID 35784659, 2022). "Another important group of genes whose alterations are associated with genomic instability are called caretaker genes, for example, BRCA1 and BRCA2, whose mutations in family groups predispose to the development of breast cancer." (PMID 35954497, 2022). "One in 6 TNBC patients have a germline BRCA 1 and/or 2 mutation (30% of breast cancer germline BRCA 1 and/or 2 population), the majority of these would be germline BRCA1 mutations." (PMID 35151316, 2022). "In breast cancer, it has been found that triple-negative breast cancer (TNBC) subtype had higher overall mutation rate in BRCA, especially BRCA1." (PMID 34979999, 2022). "In BRCA1-depleted SUM149 breast cancer cells and PDX models, treatment with an EZH2i and PARPi reduced tumour growth more than single PARPi treatment; however, this effect was not seen in a BRCA2-depleted mouse model of breast cancer." (PMID 35326684, 2022). "Mutations in breast cancer type 1 susceptibility protein (BRCA1) and its heterodimeric binding partner BRCA1-associated RING domain protein 1 (BARD1) confer a high risk for the development of breast cancer." (PMID 35408841, 2022). "The cumulative risks to age 80 years ranged from 0.4% for male breast cancer to approximately 2.5% for pancreatic cancer for BRCA1 carriers and from approximately 2.5% for pancreatic cancer to 27% for prostate cancer for BRCA2 carriers." (PMID 35077220, 2022). "The occurrence of OC and breast cancer is related to the down-regulation of STC1 after losing BRCA1 function." (PMID 35273656, 2022). "Germline mutations of BRCA1 and/or BRCA2 are observed in more than 5% of all breast cancer cases and approximately 13% of basal-like breast cancer (BLBC) cases." (PMID 36209184, 2022). "This work provides a foundation for developing off-the-shelf neoantigen-based vaccines for BRCA1-related breast cancer, yet there are several critical steps prior to achieving the vaccine development goal." (PMID 36298462, 2022).
breast cancer (continued). "Breast cancers carry BRCA1 PVs tend to be poorly differentiated, high-grade invasive ductal carcinomas, and they are more likely to be triple-negative." (PMID 36518309, 2022). "The potency of abemaciclib, palbociclib and ribociclib was investigated in a panel of 37 breast cancer cell lines presenting different molecular profiling status, including Rb1 deficiency, ER/AR expression, HER2 amplification, and PIK3CA or BRCA1/2 mutations." (PMID 35813283, 2022). "Our study provides suggestive evidence of the prognostic role of BRCA1/2 in breast cancer and the therapeutic target for breast cancer." (PMID 35409110, 2022). "By accessing and analyzing all existing gene expression data, the expression patterns, functions, and prognostic values of BRCA1/2 in breast cancer were comprehensively investigated." (PMID 35409110, 2022). "An additional case involving a transgender woman with a BRCA1-alteration went on to develop breast cancer whilst receiving androgen blocking therapy." (PMID 35804947, 2022). "Breast cancer cells depleted of BRCA1 and SMARCAL1 displayed resistance to cisplatin and the PARPi olaparib." (PMID 36568963, 2022). "Mutations of the BRCA1 and BRCA2 genes in the germline were considered resources of genetic susceptibility for breast cancer." (PMID 36713553, 2022). "The present study found that BRCA1 gene expression weakly affected the results of neoadjuvant chemotherapy in breast cancer patients, but the presence of copy number aberrations was statistically significantly associated with the tumor response to treatment." (PMID 36613648, 2022). "Women with a primary breast cancer (PBC) diagnosis and a pathogenic germline mutation in the BRCA1 or BRCA2 gene are at increased risk of developing metachronous contralateral breast cancer (CBC)." (PMID 34929424, 2022). "Except for BRCA1/2 genes that account only for 22–30% of hereditary breast cancer, less is known about the remaining genes that are prone to breast cancer." (PMID 35681739, 2022). "Oncoprint analysis of the Foundation Medicine dataset also showed that BRCA1 and BRCA2 mutations, and germline and somatic mutations, were mutually exclusive in ovarian cancer and breast cancer." (PMID 34979999, 2022). "As a disease of the genome, cancer development has a clear Mendelian component, demonstrated by several famous genes such as BRCA1 and BRCA2 in breast cancer risk." (PMID 35459932, 2022). "Among BRCA1 carriers, the minor allele of rs6138178 in SNRPB was significantly associated with lower risk of breast cancer risk." (PMID 35281269, 2022). "Overall, our study provides suggestive evidence of the prognostic role of BRCA1/2 in breast cancer and the therapeutic target for breast cancer." (PMID 35409110, 2022). "Pathogenic variants of high-risk predisposition genes such as BRCA1 and BCRA2 are the most widely known and are used in genetic testing and counseling to predict breast cancer risk and clinical outcomes." (PMID 35853889, 2022). "In conclusion, in our study, we identified 19 BRCA gene mutational variants, namely 8 BRCA1 variations and 11 BRCA2 variations, 4 of which were found in both groups of patients (ovarian and breast cancer patients)." (PMID 35409996, 2022). "In the joint analysis of BRCA1 and BRCA2 carriers, men in the uppermost PRSER+ quartile had approximately twofold increased breast cancer risk (OR = 2.10, 95% CI = 1.43 to 3.08) compared with men in the lowest quartile (available online)." (PMID 34320204, 2022).